CTSE (cathepsin E)
Description:
May have a role in immune function. Probably involved in the processing of antigenic peptides during MHC class II-mediated antigen presentation. May play a role in activation-induced lymphocyte depletion in the thymus, and in neuronal degeneration and glial cell activation in the brain.
Synonyms: CATE
Tractability: Small molecule: a high-quality ligand is known; it has a high-quality binding pocket; it belongs to a druggable protein family. Antibody: UniProt predicts a signal peptide or a membrane-spanning region. PROTAC: a small molecule that binds it is known.
Target class: Aspartic protease; Aspartic protease A1A subfamily; Protease; Enzyme; Aspartic protease AA clan
Gene: Protein-coding gene on chromosome 1 (206,008,535 to 206,023,909, reverse strand). Ensembl gene ENSG00000196188.
Subcellular location: Endosome
Subcellular location (Human Protein Atlas): Vesicles
Pathways (Reactome):
Immune System: MHC class II antigen presentation
Gene Ontology:
Molecular function: aspartic-type endopeptidase activity; peptidase activity; identical protein binding
Biological process: antigen processing and presentation of exogenous peptide antigen via MHC class II; proteolysis
Cellular component: endosome
Genetic constraint (gnomAD): Loss-of-function variants: 35 observed, 39.23 expected, observed/expected ratio (o/e) 0.89, 90% interval 0.68 to 1.18. The upper end of that interval is the gene's LOEUF score, 1.18, which puts it in group 5 of 6, group 1 being the genes least tolerant of losing a copy. Missense variants: 504 observed, 491.79 expected, observed/expected ratio (o/e) 1.02, 90% interval 0.95 to 1.1. Synonymous variants: 193 observed, 194.56 expected, observed/expected ratio (o/e) 0.99, 90% interval 0.88 to 1.12.
Homologues: Orthologues: chimpanzee CTSE (100% identical), dog CTSE (89% identical), rabbit CTSE (86% identical), macaque CTSE (84% identical), guinea pig CTSE (84% identical), rat Ctse (84% identical), mouse Ctse (83% identical), tropical clawed frog ctse (69% identical), Drosophila melanogaster Bace (43% identical), Drosophila melanogaster CG17134 (42% identical), Drosophila melanogaster CG33128 (40% identical), Drosophila melanogaster CG5863 (40% identical), and 18 more. Paralogues in human: PGA5 (53% identical), PGA3 (53% identical), PGA4 (53% identical), PGC (46% identical), CTSD (46% identical), NAPSA (44% identical), REN (37% identical), BACE1 (28% identical), BACE2 (27% identical).
Diseases named in the same sentence as CTSE in open-access papers:
CTSE is named in the same sentence as 80 diseases in open-access papers, as found by Europe PMC text mining. Sharing a sentence is not in itself a finding about the gene and the disease. The quoted sentences say what the papers report.
pancreatic cancer (10 papers, 2021 to 2025). "Cathepsin E (CTSE) is a tumor-associated intracellular enzyme, which is specifically overexpressed in a variety of cancers, including cervical, gastric, intestinal and pancreatic cancer." (PMID 36923350, 2023). "The expression levels of S100P and cathepsin E (CTSE) were significantly higher in pancreatic cancer (PC) tissues than in adjacent normal tissues." (PMID 41301873, 2025). "It is also worth noting that breast cancer was associated with elevated CTSO, pharyngeal and endometrial cancers with elevated CTSS, ovarian cancer with decreased CTSZ, prostate cancer with decreased CTSS, and pancreatic cancer with decreased CTSE." (PMID 38883596, 2024). "As for CTSE (Cathepsin E), its biological characteristics have been addressed in various tumors including pancreatic cancer, prostate cancer, and gastric cancer." (PMID 37325625, 2023). "Some studies have demonstrated that CTSE is overexpressed in tumor tissues than in normal tissues in various types of cancer, such as bladder cancer, pancreatic cancer, and hepatocellular carcinoma." (PMID 36998443, 2023). "With the help of endoscopy and immunosorbent assay (ELISA) and Western blot, CTSE was considered a better biomarker than CA19-9 for detecting pancreatic cancer." (PMID 35433683, 2022). "However, CTSS and CTSE are overexpressed in prostate cancer and pancreatic cancer, respectively; this is contrary to the results of the present study and needs to be verified by more clinical and experimental studies in the future." (PMID 38883596, 2024). "This study indicated that cathepsin E nanobiosensor is not a suitable biomarker in serum for either pancreatic cancer or pancreatitis detection." (PMID 40292193, 2024).
bladder cancer (6 papers, 2015 to 2024). "In our study, we found that overexpression of CTSE inhibited the proliferation and colony formation in different bladder cancer cell lines, which indicated the inhibition in tumor progression of CTSE." (PMID 38910160, 2024).
breast carcinoma (6 papers, 2015 to 2025). "In humans, proteins containing aspartyl protease domains includes the gene encoding Cathepsin D (CTSD), which has been implicated in breast cancer, and the gene encoding Cathepsin E (CTSE), which has been implicated in stomach cancer." (PMID 30118526, 2018). "Alternatively, however, CTSE activity levels could be studied according to a recent report, which showed that CTSE activity levels but not protein levels were associated with more advanced disease, recurrence, and prognosis in patients with breast cancer." (PMID 25348778, 2015). "We show for the first time a pro-invasive effect of VGSCs in breast cancer cells with acquired endocrine resistance, modulated in part through enhancement of proteases (cathepsin E and kallikrein 10) and MMP (such as MMP-7) activity." (PMID 26718772, 2016). "Cathepsin E has been suggested as a possible marker for pancreatic tumors, and interestingly, a recent study demonstrated a positive correlation between enhanced serum levels of cathepsin E and poor clinical prognosis in breast cancer patients." (PMID 26718772, 2016). "CTSE has been recognized as a promising prognostic biomarker for multiple cancers, such as pancreatic ductal adenocarcinoma (PDAC), gastric, esophageal, bladder, cholangiocarcinoma, rectal cancer, and breast cancer." (PMID 40467555, 2025).
prostate carcinoma (5 papers, 2013 to 2024). A carcinoma that arises from epithelial cells of the prostate gland. "In human prostate-cancer cell lines, a higher expression of CTSE induces growth arrest and apoptosis by catalyzing the proteolytic release of a tumor necrosis factor-related apoptosis-inducing ligand, which induces apoptosis." (PMID 25932638, 2015).
Alzheimer disease (4 papers, 2017 to 2024). A progressive, neurodegenerative disease characterized by loss of function and death of nerve cells in several areas of the brain leading to loss of cognitive function such as memory and language. "The function of CTSE is not well understood, however it may play a role in amyloid polyneuropathy, neuropathy in experimental autoimmune encephalitis and neuroinflammation associated with Alzheimer’s disease." (PMID 37462767, 2023). "Previous studies have found that the cathepsin E-sTRAIL axis is involved in communication between microglia and neurons during the progression of Alzheimer’s disease." (PMID 39568745, 2024). "Given that Alzheimer’s disease and AMD are diseases of aging, this indirectly suggests that cathepsin E may also play an important role in the pathogenesis of AMD and is closely associated with the cathepsin E-sTRAIL axis." (PMID 39568745, 2024). "Moreover, CtsE might also play key roles in the process of neurodegeneration since the levels of this enzyme were found upregulated in brains from patients with Alzheimer’s disease and CtsE activity was also increased in cerebrospinal fluid of Parkinson’s disease patients." (PMID 28583160, 2017).
gastric cancer (4 papers, 2013 to 2023). A primary or metastatic malignant neoplasm involving the stomach. "Summary of the association between CTSE (Cathepsin E) expression and histological type of gastric cancer using endoscopically resected specimens." (PMID 23451082, 2013). "Summary of the association between CTSE (Cathepsin E) expression and original histological type of gastric cancer cell lines." (PMID 23451082, 2013). "Summary of the association between CTSE (Cathepsin E) expression and histological type of gastric cancer using the surgical specimens." (PMID 23451082, 2013). "To analyze the relation of CTSE expression and oncogenic potential, we produced the MuLV-based retrovirus vector carrying CTSE gene and transduced it into the CTSE-deficient gastric cancer cell lines: MKN-74, SH-10-TC, and MKN-1." (PMID 23451082, 2013). "Compared with surgically specimens, the histology of endoscopically resected tissue is much more homogeneous; it was thence expected that association between CTSE expression and histology of gastric cancer could be analyzed more precisely." (PMID 23451082, 2013). "Besides, all-or-none expression of CTSE shown in RT-PCR, western blotting, and immunohistochemistry suggested that gastric cancer cells would be clearly classified into two categories: CTSE-expressing type and CTSE-deficient type." (PMID 23451082, 2013). "In contrast, CTSE overexpression has been suggested to promote gastric cancer, pancreatic ductal adenocarcinoma, cervical adenocarcinoma, and lung carcinoma development." (PMID 34357018, 2021). "The meaning and regulatory mechanism of histology-specific CTSE expression in gastric cancer are still unknown." (PMID 23451082, 2013). "From these result, we speculated that expression of CTSE is significantly correlated with histological type of gastric cancer." (PMID 23451082, 2013). "Although abundantly expressed in gastric cancer cell lines, the CTSE mRNA levels do not change between gastric tumor samples and paired normal tissues." (PMID 34357018, 2021).
gastric tumors (4 papers, 2013 to 2021). "More undifferentiated gastric tumors tend to increase expression of CTSE and MUC5AC in tumor lesions (tub2> tub1> adenoma) but decrease expression of these gastric markers in the background mucosa (tub2< tub1< adenoma)." (PMID 23451082, 2013). "Based on the result of surgical specimens, we further analyzed CTSE expression of 84 endoscopically resected gastric tumor samples." (PMID 23451082, 2013). "Expression scores of CTSE, MUC5AC, and MUC2 (from 1 to 4 respectively) in gastric tumors cells (cancer or adenoma) and adjacent normal cells (non-tumorous epithelial cells of background mucosa)." (PMID 23451082, 2013).
melanoma (3 papers, 2015 to 2024). A malignant, usually aggressive tumor composed of atypical, neoplastic melanocytes. "In the reverse causal study, melanoma was found to cause an increase in cathepsin E (OR = 1.051, 95% CI: 1.011–1.093, P < .05), while CSCC was found to cause an increase in cathepsin H (OR = 1.154, 95% CI: 1.045–1.273, P < .05) and cathepsin O (OR = 1.111, 95% CI: 1.006–1.226, P < .05)." (PMID 39312365, 2024). "In reverse Mendelian research, it was found that skin squamous cell carcinoma can increase the expression of Cathepsin H. Cathepsin E and Cathepsin O are also increased in melanoma and skin squamous cell carcinoma." (PMID 39312365, 2024). "Cathepsin E reduced murine melanoma growth in mice, when compared to tumor growth in cathepsin E knockout mice." (PMID 31333662, 2019). "Another study found that cathepsin E expressed on immune cells can cleave and activate endogenous cell surface TRAIL on prostate and melanoma cells and enhance macrophage infiltration leading to antitumor activity." (PMID 31333662, 2019). "Melanoma and CSCC may play an important role in regulating the expression of Cathepsin E, H, and O at the tumor margins." (PMID 39312365, 2024).
rectal cancer (3 papers, 2021 to 2025). A primary or metastatic malignant neoplasm that affects the rectum. "In this study, we provided evidence that overexpression of the intracellular proteinase CTSE is linked to aggressive clinicopathological parameters and functions as an independent prognostic factor for rectal cancer patients undergoing CCRT." (PMID 34357018, 2021). "Additionally, a greater comprehension of the role of CTSE in rectal cancer and its association with CCRT efficacy could make CTSE a potential predictive indicator." (PMID 34357018, 2021). "Cathepsin E (CTSE) is an adverse prognostic factor for survival among rectal cancer patients receiving chemo-radiotherapy." (PMID 36831448, 2023). "In this study, we provide the first evidence demonstrating that CTSE overexpression is significantly correlated with inferior clinical outcomes and acts as an unfavorable predictive biomarker for rectal cancer patients treated with preoperative CCRT." (PMID 34357018, 2021). "CTSE immunoreactivity in CCRT-responsive rectal carcinoma tissue specimens was significantly lower than that in CCRT-nonresponsive rectal carcinoma tissue specimens." (PMID 34357018, 2021). "Immunohistochemical staining was employed to investigate the correlations between CTSE immunoexpression and its clinical relevance in rectal carcinoma." (PMID 34357018, 2021). "This encouraged us to further explore the expression status and clinical relevance of CTSE in rectal carcinoma." (PMID 34357018, 2021). "In the present study, we evaluated genes related to digestion (GO: 0007586) and identified cathepsin E (CTSE), which is involved in immune regulation, as the most significantly upregulated gene associated with CCRT resistance in rectal cancer in a public transcriptome dataset (GSE35452)." (PMID 34357018, 2021). "Taken together, these results suggest that CTSE overexpression is related to CCRT resistance and inferior survival in rectal cancer patients, highlighting the potential predictive and prognostic value of CTSE expression." (PMID 34357018, 2021). "We recovered 172 records of rectal cancer patients receiving CCRT followed by surgical resection from our biobank and evaluated the expression level of CTSE using immunohistochemistry." (PMID 34357018, 2021). "In this study, we aimed to elucidate the role of CTSE in response to preoperative CCRT and correlate CTSE expression with clinical outcomes in our well-characterized rectal cancer cohort." (PMID 34357018, 2021).
atopic dermatitis (2 papers, 2020). "CTSE knockout mice exhibit a reduced turnover of interleukins that accumulate systemically, which likely initiates the development of atopic dermatitis." (PMID 33575564, 2020). "Consistent with an involvement of CTSE in this disease, human atopic dermatitis patients show reduced CTSE expression." (PMID 33575564, 2020). "To conclude, this study showed that the GCF concentrations of ADAM8, ADAM9, Cathepsin E, MMP8, CD10, Protein convertase 9, and uPA/Urokinase proteases were downregulated in moderate/severe atopic dermatitis patients compared to healthy controls." (PMID 33255937, 2020).
Barrett esophagus (2 papers, 2015 to 2021). Esophageal lesion lined with columnar metaplastic epithelium which is flat or villiform. "We evaluated CTSE in Barrett’s esophagus (BE) and cancer because increased CTSE levels are linked to improved survival in several cancers, and other cathepsins are up-regulated in BE and esophageal adenocarcinoma (EAC)." (PMID 25348778, 2015). "A similar pattern was found in cathepsin E whose expression was significantly higher in Barrett’s esophagus than normal tissue, but esophageal adenocarcinoma expressed a relatively lower cathepsin E level than Barrett’s esophagus." (PMID 33990205, 2021). "This study aimed to evaluate the potential prognostic value of CTSE to predict progression to more advanced disease in patients with Barrett metaplasia–dysplasia–adenocarcinoma spectrum, and to predict survival for patients with EAC." (PMID 25348778, 2015).
chronic pancreatitis (2 papers, 2014 to 2020). A chronic inflammatory process causing damage and fibrosis of the pancreatic parenchyma. "Patients with pancreatic diseases (chronic pancreatitis) had a higher risk of developing PDAC and thus the expression of CTSE in pancreatic diseases might be the key to early PDAC detection and PDAC progression." (PMID 33178697, 2020).
colon cancer (2 papers, 2015 to 2021). "Robust markers of metaplasia in our study included cathepsin E (CTSE), which has been associated with gastric and colon cancers and previously shown to be upregulated in patients with BAR and EAC, as well as the anion/bicarbonate channel CFTR and PDZ-domain-containing mucins MUC17, MUC3A, and MUC12." (PMID 34412659, 2021). "Cathepsin E (CTSE), an aspartic proteinase, is differentially expressed in the metaplasia–dysplasia–neoplasia sequence of gastric and colon cancer." (PMID 25348778, 2015).
endothelial dysfunction (2 papers, 2023 to 2024). In vascular diseases, endothelial dysfunction is a systemic pathological state of the endothelium (the inner lining of blood vessels) and can be broadly defined as an imbalance between vasodilating and vasoconstricting substances produced by (or acting on) the endothelium. "By activating inflammatory mediators, cathepsin E could contribute to endothelial dysfunction leading to MI and IS." (PMID 39027333, 2024).
hepatocellular carcinoma (2 papers, 2023 to 2025). A malignant tumor that arises from hepatocytes. "In this study, we analyzed hepatocellular carcinoma (HCC) single-cell sequencing of public databases to investigate cellular interactions, revealing that cathepsin E (CTSE) highly expressed cancer cells exhibited significant interactions with T cells." (PMID 40467555, 2025).
ischemic stroke (2 papers, 2024). A stroke disorder caused by obstruction of blood flow to the brain, due to thrombotic (local blood clot formation) or embolic (due to a blood clot or other material traveling from another site) event. "The cathepsin E increases the risk of myocardial infarction (MI) (OR = 1.053%, 95% CI: 1.007–1.101, p = 0.024) and ischemic stroke (IS) (OR = 1.06%, 95% CI: 1.019–1.103, p = 0.004)." (PMID 39027333, 2024). "Conversely, elevated levels of Cathepsin E (OR: 1.05, 95%CI: 1.01, 1.09, p = 0.015) and Cathepsin O (OR: 1.05, 95%CI: 1.01, 1.10, p = 0.021) were associated with an increased risk of ischemic stroke." (PMID 39420987, 2024). "Conversely, Cathepsin E and Cathepsin O were found to be risk factors for ischemic stroke." (PMID 39420987, 2024). "However, existing research on the correlation between Cathepsin E and ischemic stroke is limited, highlighting the necessity for more comprehensive studies to uncover the underlying mechanisms." (PMID 39420987, 2024). "The upregulation of Cathepsin E may potentially hasten the progression of ischemic stroke." (PMID 39420987, 2024).
lupus (2 papers, 2019 to 2024). "The CTSE gene exhibits higher expression in MRL/lpr lupus-prone mice compared to control C57BL/6 mice." (PMID 39736788, 2024). "Overexpression of CTSE may compensate by upregulating defective mitochondria, suppressing autophagy, and mitigating lupus severity." (PMID 39736788, 2024).
lysosomal storage disorder (2 papers, 2015 to 2025). "Involvement of the endolysosomal aspartic protease CTSE in autophagy was proposed by Kaminsky and Zhivotovsky based on the observation that macrophages from CTSE-deficient mice displayed a lysosomal storage disorder." (PMID 26226952, 2015).
Pancreatic (2 papers, 2014 to 2024). "Cathepsin E activity levels remained similar for all disease groups, except for localized pancreatic cancer and pancreatitis." (PMID 40292193, 2024). "All eight nanobiosensors (arginase, cathepsin B, cathepsin E, MMP1, MMP3, MMP9, neutrophil elastase, and uPA) were used to measure enzymatic activity in serum samples from four different disease groups: localized pancreatic cancer, metastatic pancreatic cancer, pancreatitis, and a ‘healthy’ control." (PMID 40292193, 2024).